SRSF12 (serine and arginine rich splicing factor 12)
Description:
Splicing factor that seems to antagonize SR proteins in pre-mRNA splicing regulation.
Synonyms: SRrp35; SFRS13B; SFRS19
Tractability: PROTAC: its protein half-life has been measured.
Gene: Protein-coding gene on chromosome 6 (89,093,949 to 89,118,071, reverse strand). Ensembl gene ENSG00000154548.
Subcellular location: Nucleus
Pathways (Reactome):
Metabolism of RNA: Processing of Capped Intron-Containing Pre-mRNA; mRNA Polyadenylation; mRNA Splicing - Major Pathway
Gene Ontology:
Molecular function: protein binding; RNA binding; RS domain binding; nucleic acid binding
Biological process: mRNA 5'-splice site recognition; regulation of alternative mRNA splicing, via spliceosome; negative regulation of mRNA splicing, via spliceosome; spliceosomal tri-snRNP complex assembly
Cellular component: nucleoplasm; nucleus
Genetic constraint (gnomAD): Loss-of-function variants: 18 observed, 33.32 expected, observed/expected ratio (o/e) 0.54, 90% interval 0.37 to 0.8. The upper end of that interval is the gene's LOEUF score, 0.8, which puts it in group 3 of 6, group 1 being the genes least tolerant of losing a copy. Missense variants: 278 observed, 332.57 expected, observed/expected ratio (o/e) 0.84, 90% interval 0.76 to 0.92. Synonymous variants: 111 observed, 112.89 expected, observed/expected ratio (o/e) 0.98, 90% interval 0.84 to 1.15.
Homologues: Orthologues: chimpanzee SRSF12 (100% identical), macaque SRSF12 (100% identical), pig SRSF12 (98% identical), dog SRSF12 (92% identical), rat Srsf12 (91% identical), guinea pig SRSF12 (89% identical), tropical clawed frog srsf12 (73% identical), rabbit SRSF12 (62% identical), mouse Srsf12 (59% identical), zebrafish srsf10a (19% identical). Paralogues in human: SRSF10 (56% identical), SRSF2 (36% identical), SRSF8 (31% identical).
Diseases named in the same sentence as SRSF12 in open-access papers:
SRSF12 is named in the same sentence as 2 diseases in open-access papers, as found by Europe PMC text mining. Sharing a sentence is not in itself a finding about the gene and the disease. The quoted sentences say what the papers report.
cancer (3 papers, 2023 to 2025). A tumor composed of atypical neoplastic, often pleomorphic cells that invade other tissues. "To investigate which genes are subject to AS by SRSF12, we correlated PSI values of each ASE across cancer cells with SRSF12 expression in each individual cell." (PMID 41273175, 2025). "For example, SRSF12 presented CNV deep deletion in LIHC, LUAD, and PRAD, however showing higher expression in cancer tissues." (PMID 38015716, 2023). "For example, SRSF12 displayed CNV deep deletion in LIHC, LUAD, and PRAD; however, showing higher expression in cancer tissues." (PMID 38015716, 2023).
tumor (1 paper, 2023). "Furthermore, our results highlight a function for SRSF12 in pro-inflammatory macrophages, key cells in the tumor response." (PMID 37359548, 2023). "Furthermore, our results show a new function for SRSF12 in pro-inflammatory macrophages, which may be important for the tumor response." (PMID 37359548, 2023).